BECN1 (beclin 1)
Diseases named in the same sentence as BECN1 in open-access papers (continued):
Sharing a sentence is not in itself a finding about the gene and the disease.
ischemia (continued). "Administration of 200 mg/kg/day metformin i.p. for 6 successive days before induction of ischemia and promptly at the onset of reperfusion to rats enhanced eNOS, HO-1, CSE, and Beclin-1 protein expressions." (PMID 39912902, 2025). "DIM (1, 10 μM) partially normalized ischemia-induced changes i.e., it reduced the AhR, CYP1A1, Fas, and BECN1 immunolabeling." (PMID 30778709, 2019). "DIM also reduced protein levels of autophagy-related BECN1 and LC3, partially reversed the ischemia-induced decrease in NUP62 and inhibited autophagosome formation." (PMID 30778709, 2019). "Daily administration of 200 mg/kg metformin concurrently with 1mg/kg RAPA i.p. for 6 successive days before induction of ischemia and promptly at the onset of reperfusion to rats raised the stimulatory effect of metformin on eNOS, HO-1, CSE, and Beclin-1 protein expressions in the liver tissue." (PMID 39912902, 2025). "The myocardial protection of adenosine A2a receptor after ischemia may involve the cAMP-PKA signaling pathway and the interaction of Bcl-2-Beclin-1." (PMID 35571159, 2022). "The results also revealed that the expression of miR-30d-5p could significantly inhibit the expression of Beclin-1 and Atg5- by targeting the 3′UTR levels of Beclin-1 and Atg5- and inhibit the ischemia-induced polarization of microglia to M1." (PMID 35585925, 2022). "Moreover, another study also showed that Beclin-1 protein and LC3B protein levels markedly increased in model groups with 2 h ischemia followed by 72 h reperfusion compared with the sham group." (PMID 34917161, 2021). "The LC3-II and BECN1 levels, which are representative autophagy markers, were not changed at the end of the ischemia or immediately after reperfusion." (PMID 29706629, 2018).
pancreatic cancer (49 papers, 2010 to 2025). "While disruption of beclin-1, the mammalian ortholog of yeast Atg6, has been shown to promote tumorigenesis in mice, and in pancreatic cancer, overactivity of the autophagosomal pathway is associated with aggressiveness and negative prognosis." (PMID 36831186, 2023). "Collectively, these findings suggest that RCE induces Beclin-1-independent autophagy in human pancreatic cancer cells." (PMID 39139643, 2024). "It is important to note that in the present study, RCE induced Beclin-1-independent autophagy and decreased BCl-2 protein levels in pancreatic cancer cells." (PMID 39139643, 2024). "Our results demonstrate that RCE induces its anticancer effects in human pancreatic cancer cells through induction of G1 cell cycle arrest, Beclin-1-dependent autophagy, and apoptosis." (PMID 39139643, 2024). "The antiproliferative effects of RCE in pancreatic cancer cells (Panc-1 and Mia-PaCa-2) were mediated through induction of G1 cell cycle arrest, Beclin-1-independent autophagy, and apoptosis." (PMID 39139643, 2024). "Autophagy-induced apoptosis was associated with parthenolide treatment in triple-negative breast cancer cells and pancreatic cancer cells by increasing the expression of beclin-1, LC3II, and p62/SQSTM1." (PMID 37298119, 2023). "Nevertheless, further evidence is needed to assess the prognostic impact of Beclin 1 expression levels in pancreatic cancer." (PMID 34559451, 2021). "Another study showed that miR-216a can render radioresistant pancreatic cancer cells radiosensitive by inhibiting beclin-1-mediated autophagy." (PMID 33317198, 2020). "Similar to our data, it has been reported that Beclin-1 silence not only increases the autophagic process, but also decreases apoptosis in gemcitabine-treated pancreatic cancer MIA PaCa-2 cells." (PMID 32252439, 2020). "Gambogic acid induced the expression of LC3-II and Beclin-1 proteins in pancreatic cancer cells, whereas the expression of P62 showed a decline." (PMID 30627053, 2019). "DHA triggered autophagy by up-regulating the Beclin 1 expression to induce cell death in pancreatic cancer cells, and stimulated autophagy through repression of NF-κB activity to induce cell death in human multiple myeloma cancer cells." (PMID 29033794, 2017). "Although, Beclin 1 up-regulation by JNK was observed after autophagy induced by the anticancer drug topotecan, the data presented in the present study constitute the first evidence that Beclin 1 is regulated by JNK in pancreatic cancer cells." (PMID 24438216, 2014). "More importantly, siRNA-mediated JNK down-regulation prevented the DHA-induced up-regulation of Beclin 1 protein in addition to efficiently inhibiting the level of JNK phosphorylation in pancreatic cancer cells." (PMID 24438216, 2014). "ROS can increase the release of HMGB1 from necrotic cells and then activates Beclin-1-dependent autophagy by binding to AGER in pancreatic cancer cells." (PMID 25197670, 2014). "Moreover, in pancreatic cancer, previous study confirmed that phosphorylation at S90/93/96 facilitates the binding of beclin 1 to xCT, resulting lipid peroxidation and ferroptosis, eventually extending the survival time of mice." (PMID 39557844, 2024). "This is particularly interestingly, and further supports the argument that RCE-induced autophagy preceded apoptosis in pancreatic cancer cells, as Beclin-1-independent autophagy is reported to play a pro-death role over a pro-survival role through induction of apoptosis." (PMID 39139643, 2024). "Beclin-1, the first identified autophagy-related protein in cancer, has previously been identified as the direct target of miR-30a in various cancer types, including small cell lung cancer, pancreatic cancer, and cervical cancer, etc20–25." (PMID 32251287, 2020).
pancreatic cancer (continued). "Bovine seminal RNase (BS-RNase) triggers an autophagic cell death process in pancreatic cancer cells mediated by BECN1 induction; and onconase, a RNaseA superfamily member proposed for chemotherapy, inhibits the proliferation of cancer cells through the ROS/Akt/mTOR pathway." (PMID 31312205, 2019). "We wondered if the Beclin-1/p62/c-Myc signaling pathway is activated and functions in pancreatic cancer and whether EI24 plays a role in this pathway." (PMID 30369947, 2018). "To first clarify whether the suppression of pancreatic cancer tumorigenicity induced by EI24 was associated with autophagy, we examined Beclin-1, which is essential for autophagy upregulation, by immunofluorescence analysis in xenograft tissues." (PMID 30369947, 2018). "In other reports, however, it could enhance the sensitivity of NSCLC cells to CDDP treatment and enhance the radiosensitivity of pancreatic cancer cells by inhibiting beclin-1-mediated autophagy." (PMID 26989293, 2016). "However, Beclin-1 expression was reported to be increased in human colon, gastric, and pancreatic cancers, in contrast to their normal counterparts." (PMID 23578251, 2013). "Bax can directly inhibit autophagy, and treatment of pancreatic cancer cells with 4-AAQB enhances the expression of pro-apoptotic protein Bax and reduces the expression levels of autophagy-related proteins (Atg5, Beclin-1, and LC3 II)." (PMID 38529373, 2024). "In pancreatic cancer, RAGE-mediated autophagy acts by reducing the phosphorylation level of mammalian target of rapamycin (mTOR) and limiting the formation of the Beclin-1/VPS34 autophagy complex." (PMID 38529373, 2024). "To determine the role of autophagy in pancreatic cancer stemness, we established lentivirus-mediated stable ATG5, ATG7, and BECN1 knockdown cell lines shATG5, shATG7, and shBECN1 derived from PANC-1 cells and analyzed their CSC activity." (PMID 26458814, 2015). "Additionally, a previous study demonstrated that LINC01207 silencing promotes autophagy in pancreatic cancer by increasing LC3II and beclin-1 protein expression while decreasing P62 expression." (PMID 34463208, 2021). "Other groups reported that the IL-6/JAK2 signaling pathway inhibits autophagy, via p-STAT3, which activates Bcl-2 to regulate the expression of Beclin 1 and VPS34, while in pancreatic cancer, IL-6 induces mitochondrial localization of p-STAT3 at Ser727, upregulating autophagy flux." (PMID 32565533, 2019). "Interestingly, another miRNA, miR-216a, that is also downstream of TGF-β signaling and miR-192, has been shown to target BECN1 and ATG5 expression in endothelial cells and Becn1 in pancreatic cancer cells." (PMID 29725042, 2018). "CaCO3@CM-OA treatment also increased the expression of Beclin 1 and LC3B/LC3A, indicating the activation of autophagy signaling pathway Detection of N-cadherin and Vimentin showed that CaCO3@CM-OA also inhibited the epithelial-mesenchymal transition (EMT) process of pancreatic cancer in vivo." (PMID 41377584, 2025). "Furthermore, the iron-binding nuclear protein pirin (PIR) can hijack HMGB1 in the nucleus, thereby inhibiting the translocation of HMGB1 to the cytoplasm and subsequent activation of beclin 1 (BECN1)-dependent autophagy and ferroptosis in pancreatic cancer cells." (PMID 36845736, 2023). "Since ATG5 and Beclin 1 are both known to be direct targets of miR-30a, we hypothesized that YY1 and miR-30a might form a functional regulatory circuit that modulates autophagy in pancreatic cancer cells." (PMID 29052509, 2017). "The research about pancreatic cancer stem cells found that rottlerin could reduce the viability of pancreatic cancer stem cells and induce apoptosis to form cytoplasm cavity and upregulate autophagy markers LC3-I, LC3-II, Atg7, and Beclin-1." (PMID 29234398, 2017). "However, increased sensitivity to chemotherapeutic agents in RAGE-knockdown pancreatic cancer cells is dependent on ATG5 expression but independent of BECN1 expression." (PMID 25197670, 2014).
pancreatic cancer (continued). "Our results demonstrated that Beclin 1 expression and conversion of the cytosolic form of LC3B-I to its lipidated membrane-bound form LC3B-II were increased in the Panc1 cell GnRH-OE group, suggesting that autophagy may be involved in GnRH-mediated apoptosis in pancreatic cancer cells." (PMID 31263453, 2019).
liver cancer (48 papers, 2011 to 2025). An epithelial or non-epithelial malignant neoplasm that arises from the liver. "Researches have revealed that beclin-1 is a tumor suppressor and that beclin-1 deficiency can promote the formation and transformation of liver cancer cells." (PMID 24287900, 2013). "A single allele loss of Beclin-1 was observed in 40–75% of breast, prostate, and ovarian tumors, and a severely reduced expression of Beclin-1 was observed in prostate, ovarian, colon, brain, breast, and liver cancers." (PMID 37736508, 2023). "Additionally, autophagy can induce the replication of a DNA virus via the upregulation of PI3K class III and/or Beclin-1 in liver cancer, which is also known to cause hepatitis B viral infection." (PMID 33415148, 2020). "It is not hard to understand that the expression level of Beclin 1 may be a valuable prognostic marker of liver cancer and loss or lower expression of Beclin 1 may suggest an inferior prognosis of HCC." (PMID 28915706, 2017). "A previous study found that the hydroxysafflor yellow A induced autophagy by promoting the expression of Beclin-1 in liver cancer cells, similar to our results." (PMID 38603936, 2024). "In liver cancer cells, the overexpression of NOS2 and NOS3 induces a transition between apoptosis and autophagy by disrupting the Beclin 1/Vps34 association and increasing the Bcl-2/Beclin 1 interaction." (PMID 37958916, 2023). "For instance, bufalin induces cell autophagy and inhibits the proliferation of liver cancer cells by influencing the expression of autophagy-related proteins including LC3-I, LC3-II, P62, and Beclin-1 in liver cancer cells." (PMID 36091810, 2022). "We have identified the dysregulation of AKT, mTOR, p62, LC3, and Beclin 1, which has led to the initiation of cell death by Lanatoside C in breast, lung, and liver cancer cells." (PMID 31783627, 2019). "miR-376a and miR-376b regulated starvation- and rapamycin-induced autophagy in breast and liver cancer cells by directly targeting 3′-UTR sequences of BECN1/Beclin 1 and ATG4C." (PMID 28459042, 2017). "Inducing mitochondrial apoptosis in liver cancer cells and activating autophagic cell death in liver cancer cells by activation of Beclin-1 and suppressing the mTOR-signaling pathway." (PMID 26633388, 2015). "The results differ from those reported in liver cancer cells and cervical cancer cells, which showed Beclin 1 expression significantly lower compared to the corresponding normal tissues." (PMID 23029344, 2012). "In liver cancer cells such as HepG2 and MHCC97-L, berberine may also cause autophagic cell death through activation of Beclin-1 and inhibition of the mTOR-signaling pathway by downregulating Akt activity and upregulating P38 MAPK signaling." (PMID 36144625, 2022). "A previous study found that highly upregulated in liver cancer (HULC) bound to Beclin-1, then inhibited Beclin-1 phosphorylation, and it could result in decreased autophagy via the modulation of the mTOR signaling pathway." (PMID 30153654, 2018). "Beclin 1 has a critical, regulatory role in autophagy, and downregulation of Beclin 1 has previously been shown to sensitize Hela human cervical cancer cells and HepS mouse liver cancer cells to cisplatin." (PMID 25322694, 2015). "However, there are opposing data on the effect of HDAC6 on Beclin-1 expression obtained on liver cancer cells, showing that HDAC6 overexpression activated c-Jun NH2-terminal kinase (JNK) and increased the phosphorylation of c-Jun, which induced Beclin-1-dependent autophagy." (PMID 38258065, 2023). "However, a recent study has shown that CMA may inhibit macroautophagy through the degradation of Beclin 1, thereby resulting in p62 accumulation, a characteristic feature of liver cancer nodules." (PMID 35159028, 2022). "Conversely, in liver cancer, CDDP-induced drug resistance correlates with lowered mTOR signaling with increased autophagy, as evidenced by elevated Beclin-1, increased LC3B-II, and reduced p62." (PMID 38560690, 2024).
liver cancer (continued). "In addition to BECN1/Beclin 1, miR-376 family members miR-376a and miR-376b could negatively regulate ATG4C in breast and liver cancer cells." (PMID 28459042, 2017).
lymphoma (44 papers, 2011 to 2025). A malignant (clonal) proliferation of B- lymphocytes or T- lymphocytes which involves the lymph nodes, bone marrow and/or extranodal sites. "The altered expression of BCL2 and BECN1 correlates with lymphoma outcomes, but whether this is associated with dysregulated cross-talk between autophagy and apoptosis remains to be elucidated." (PMID 37566004, 2023). "An initial study indicated that inhibiting Beclin-1 accelerated the progression of premalignant lesions caused by agents like the hepatitis B virus, enhanced the emergence of spontaneous cancers in the lung, liver, and lymphomas, and promoted mammary hyperplasia." (PMID 39403142, 2024). "This study suggests that the triterpenoid GA-DM differentially influences mitochondrial membrane potential in mouse and human lymphoma cells, possibly by regulating Beclin-1 expression in A20 cells and caspase 3 in DB and Toledo cells." (PMID 40002858, 2025). "In certain cell-based assays, autophagy suppression promoted cancer cell growth, and Becn1 heterozygous mutant mice were prone to liver and lung tumors and lymphomas with long latency." (PMID 34257560, 2021). "Beclin-1−/− (in all tissues) mice die early in embryogenesis and beclin-1−/+ increased frequency of spontaneous malignancies, especially lymphomas, decreased pressure overload-induced heart failure, and decreased cardiac injury during ischemia/reperfusion." (PMID 33233671, 2020). "While beclin 1−/− mice die early in embryogenesis, mammary tissue from beclin 1+/- mice shows hyperproliferative, preneoplastic changes, and aging beclin 1+/- mice have an increased incidence of lymphoma and carcinomas of the lung and liver." (PMID 23840208, 2013). "Heterozygous disruption of Beclin 1 increased the incidence of sporadic malignancies in mice, including lymphoma." (PMID 21611191, 2011). "Also, down‐regulation of BECN1 has been reported in several cancers, including non‐small cell lung, brain, lymphomas, melanomas, and osteosarcomas." (PMID 36760166, 2023). "For instance, while Becn1 gene is a master player in multiple steps of autophagy, Becn1 mutant mice (Becn1+/-) were prone to developing spontaneous lymphoma compared with Becn1 wild-type mice, indicating the tumor suppressor role of autophagy on tumor initiation." (PMID 33076962, 2020). "Therefore, we also examined the effect of Beclin 1 gene dosage in Lck-Bax1 mice, which develop lymphoma with only about 50% penetrance at one year." (PMID 21611191, 2011). "The expression of key autophagy-relevant proteins (e.g. Beclin-1, ULK1) and LC3 processing was increased in cHL cells, even in lymphoma cases." (PMID 27366944, 2016). "Four antigens, TCEB3, BECN1, c14orf93, and ZBTB44, showed more frequent recognition by lymphoma patients' sera." (PMID 21887344, 2011). "Compared with those in control tissue, lymphoma showed significant increases of in LC3B (LC3BI represents early autophagy, while LC3BII represents autophagic flux), autophagy related 14 (Atg14) and Beclin-1 levels, and a decrease in p62 (sequestosome 1) levels." (PMID 40296899, 2025). "Our data reveal, for the first time, that the modulation of BECLIN-1-dependent autophagy influences the prognosis of DLBCL patients and provide a mechanistic explanation supporting the therapeutic use of drugs that, by stimulating autophagy, can sensitize lymphoma cells to chemotherapy." (PMID 37566004, 2023). "However, this does not exclude the possibility that the five antigens preferentially recognised by sera from patients (TCEB3, BECN1, CEP250, c14orf93 and ZBTB44) may have a role in the pathobiology of lymphoma." (PMID 21887344, 2011). "Again, our results show that Beclin 1+/− did not affect lymphoma formation in Lck-Bax1 mice." (PMID 21611191, 2011).
lymphoma (continued). "BCL-2 levels showed a negative correlation with p62 in FL (P<0.05) and positive correlation with p62, LC3 or Beclin-1 in DLBCL (P<0.01), suggesting that BCL-2 does not play a dominant role in autophagy status in these lymphomas." (PMID 25362242, 2014).